MMP1 (matrix metallopeptidase 1)
Diseases named in the same sentence as MMP1 in open-access papers (continued):
Sharing a sentence is not in itself a finding about the gene and the disease.
tendinopathy (20 papers, 2011 to 2025). "In the early phase of tendinopathy, inflammation due to the response of the immune system causes damage to the tendon with induction of MMP-1 and MMP-13 expression as tendon catabolic markers." (PMID 32041254, 2020). "Specifically, in tendon disease, cathepsins K and L7,21, MMP-1, -2, and -13, and their endogenous inhibitors, are dysregulated in rat and human tendinopathy." (PMID 30931961, 2019). "Others21, 23 have reported significantly elevated MMP-1 and -3 expression after IL-1β stimulation in human tendon cells and have made IL-1β a candidate for an in vitro tendinopathy model." (PMID 28091588, 2017). "HMW-HA attenuated tendinopathy by downregulating MMP-1 and -3 expression." (PMID 28091588, 2017). "MMP-1 polymorphisms may alter collagen types I and III of tendon, which contribute with higher risk of tendinopathy development." (PMID 27930691, 2016). "This prompted us to examine whether the increased collagen matrix contraction in response to HMC-1 could be due to increased expression of MMPs that are known to play a role in tendinopathies, including MMP1 and MMP7." (PMID 24517261, 2013). "In collagenase-induced tendinopathy mice, a single SM102-Il1rn mRNA injection attenuated inflammation, reduced MMP1/13 expression, and improved collagen alignment within 1 week." (PMID 40873435, 2025). "The results showed that tendinopathy tenocytes had higher levels of COL3A1, MMP1, COX2, SCX, ACTA2, and substance P gene expression compared to healthy tenocytes." (PMID 28598390, 2017). "After SP treatment in our cultured healthy cells, levels of COL3A1, MMP1, and ACTA2 genes were increased, which were also shown in the tendinopathy samples." (PMID 28598390, 2017). "This study demonstrates that IL-1β mimics some aspects of tendinopathies with PGE2 induction, MMP expression (mostly MMP1 and MMP3), and increases of type III/I collagen ratio." (PMID 26156631, 2015). "Given that impaired mechanical loading increases MMP1 and ADAMTS5 in synovial cells, our results might partly reflect the upregulation of mechanical stress factors due to tendinopathy." (PMID 35168639, 2022). "As shown in the results comparing the healthy and tendinopathy samples, the relative mRNA expressions of COL3A1, COX2, SCX, MMP1, and ACTA2 were increased by 1.4, 1.8, 2.7, 1.3, and 1.6 times in the SP-treated samples compared to the PBS-controls (p < 0.05 in all), respectively." (PMID 28598390, 2017). "Moreover, VAS scores and MMP-1 and -3 expression were significantly lower in patients with LHB tendinopathy who had been treated with HMW-HA." (PMID 28091588, 2017). "In short, the present studies outline potential mechanisms by which mast cells could contribute to the pathogenesis of tendinopathy, and implicate the involvement of TGF-β1, PGE2, and MMPs (notably MMP1 and MMP7) in the response of tenocytes to mast cells." (PMID 24517261, 2013). "In contrast, MMP1 was upregulated in human patellar tendinopathy and increased expression of MMP1 was found in tendon ruptures Additionally, upregulation of MMP2 and MMP9 was shown to be a feature of tendinopathy and increased MMP9 activity was seen after exercise." (PMID 35008516, 2021). "Therefore, we hypothesized that HMW-HA downregulates MMP-1 and -3 expression by stimulating CD44 receptor in tendinopathy." (PMID 28091588, 2017). "However, MMP1, MMP13, MMP10, ADAMTS5, TIMP3, versican, aggrecan, biglycan, decorin, fibronectin, fibrillin and COMP showed an opposite response with strain compared to tendinopathy." (PMID 23830915, 2013). "The lack of expression of MMP1 and MMP13, which are known to be induced by inflammatory cytokines, further supports the proposal that pro-inflammatory cytokines do not play a major role in tendinopathy at this late stage of disease." (PMID 21539748, 2011).
fibrosis (19 papers, 2013 to 2025). the formation of excess fibrous connective tissue in an organ or tissue in a reparative or reactive process. "Among the biomarkers, matrix metalloproteinase-1 (MMP-1) showed a significant difference across fibrosis groups (p = 0.009)." (PMID 40572790, 2025). "MMP-1 breaks down the interstitial collagens types I, II and III, and is associated with fibrosis in SSc." (PMID 36688692, 2023). "In our previous study, we found that MMP-1 of human WJ-MSCs alleviated skeletal muscle fibrosis in mdx mice and in an in vitro fibrosis model." (PMID 34572277, 2021). "The levels of TIMP-1 were positively correlated with the level of liver inflammation and fibrosis, and the levels of MMP-1 were negatively correlated with the level of fibrosis." (PMID 32928296, 2020). "IL-17 is an effective inducer of matrix metalloproteinase-1 (MMP-1) in human cardiac fibroblasts, which may have potential implications in cardiac fibrosis, remodeling, and heart failure through various pathways." (PMID 37507655, 2023). "MMP1 and TGF-β1 play an important role in the formation of pulmonary scarring and fibrosis." (PMID 37221600, 2023). "Additionally, the MMP-1 and MMP-3 secreted by senescent cells during oral submucosal fibrosis have been shown to promote fibrosis in the advanced stages." (PMID 36275775, 2022). "Our results, however, demonstrate that the serum level of MMP-1 was not significantly different between severe and nonsevere fibrosis stages." (PMID 35715541, 2022). "Fibrosis may also be stimulated by upregulating the MDA/4-HNE pathway; this pathway will, in turn, upregulate pro-fibrogenic matrix metalloproteinase-2 (MMP2) and downregulate matrix metalloproteinase-1 (MMP1), two enzymes responsible for remodeling the hepatic extracellular matrix." (PMID 38214802, 2024). "The serum levels of MMP-1 and collagen IA1 were not significantly different between severe and nonsevere fibrosis stages (p value = 0.570 and p value = 0.970, respectively)." (PMID 35715541, 2022). "MMP-1 is known to have anti-fibrotic effects, but it has not been confirmed whether MMP-1 is effective in an H2O2-induced fibrosis model." (PMID 32872523, 2020).
liver cancer (19 papers, 2010 to 2025). An epithelial or non-epithelial malignant neoplasm that arises from the liver. "Rd has been shown to inhibit migration of liver cancer cell lines HepG2 by reducing expression of MMP-1, MMP-2 and MMP-7." (PMID 24130681, 2013). "MMP-1 is considered the main marker of success of immunotherapy in liver cancer." (PMID 38067256, 2023). "MMP1 also enhances liver cancer 37 and endometrial cancer 43 proliferation." (PMID 35414794, 2022). "In addition to the EMT regulated by Snail, nuclear Snail was also reported to play an another key role in regulating cell invasion by inducing increases in MMPs, such as MMP-1, MMP-2, MMP-7, MMP-9, and MMP-14, in ovarian, oral, and liver cancers." (PMID 36766694, 2023). "Some other studies had demonstrated that praeruptorin A could inhibit the migration and invasion of liver cancer cells, and inhibit the expression of the MMP1 gene by activating the extracellular signal-regulated kinase (ERK) signaling pathway, thereby inhibiting the movement of liver cancer cells." (PMID 34194480, 2021). "In this study, the mRNA expression of integrins and MMPs that was detected in different liver cancer cell lines and MHCC97H cells was found to feature low levels of integrin α5 mRNA expression and high levels of integrin αv, integrin β1, integrin β3, MMP1, MMP2 and MMP9 mRNA expression." (PMID 20939933, 2010).
glioblastoma (18 papers, 2010 to 2025). The most malignant astrocytic tumor (WHO grade IV). "Five articles addressed the MMP1–1607 polymorphism in nervous system cancers, including astrocytoma, glioblastoma, hypophyseal adenoma, and malignant gliomas." (PMID 30627228, 2018). "Even when correlating glioblastomas versus astrocytomas, we showed a significantly increased level of MMP1, MMP3, MMP13, and TIMP1." (PMID 38474106, 2024). "High-grade tumors exhibit a significant excess of NO synthase, and it has been proven that in glioblastoma cells exposed to NO, there was a marked increase in MMP-1 expression." (PMID 36291686, 2022). "MMPs have been shown to contribute to tumorigenicity; the over-expression of MMP1 enhances tumorigenicity, while its knockdown reduces tumor formation in a glioblastoma cell line." (PMID 23626764, 2013). "MMP1 is highly expressed in glioblastoma multiforme xenografts." (PMID 35954348, 2022). "Moreover, GBP1 is induced by EGFR signaling and promotes invasion because it is required for the EGF-induction of MMP1 in glioblastoma." (PMID 34439200, 2021). "Expression of several MMPs, including MMP-1, -2, -7, and -9, correlates with tumor grade, whereas MMP-3 appears to play a limited role in glioblastoma progression." (PMID 41515435, 2025). "An elevation in the protein levels of MMP1, MMP2, MMP3, and MMP8 was observed in astrocytoma samples, whereas a decrease in the amount of these proteins was noted in the glioblastoma group compared to the control group." (PMID 38474106, 2024). "An increase in the protein levels of MMP1, MMP2, MMP3, and MMP8 was observed in astrocytoma samples, while a reverse trend was noted, with a decrease in the amount of these proteins in the glioblastoma group when compared to the control group." (PMID 38474106, 2024). "In glioblastomas, YAP confers invasiveness by upregulating miR296-3p as well as other canonical YAP targets (neuronal growth regulator 1 (NEGR1), matrix metalloproteinase 1 (MMP1), endothelin 1 (EDN1), CYR61, and CTGF)." (PMID 34439395, 2021). "Moreover, cell invasion and expression of the matrix metalloproteinase genes MMP1 and MMP2 are significantly enhanced by CAV1 in glioblastoma cells." (PMID 29340103, 2017). "Moreover, our analyses revealed a downregulation of HEF1/NEDD9 and of metallo-matrixproteases pro-MMP1 and pro-MMP2 in SOX2-depleted U343-MG and U373-MG glioblastoma cells." (PMID 22070920, 2011). "IFN-γ treatment of glioblastoma cells to induce GBP-1 does not induce MMP-1." (PMID 35681772, 2022). "There, genes with a higher expression in glioblastoma compared to astrocytoma were VEGFA, 4EBP1, CCL2, PLAU (uPA), CXCL8 (IL8), CXCL10 (IP10), CASP8, HGF, LIF, CD40, CDCp1, TNFRSF11B (OPG), CD274 (PD-L1), IL6, CXCL1, CCL20 (MIP3α), CCL8 (MCP2), CD244, MMP1, TNFRSF9, CXCL6, MMP10, FGF5)." (PMID 35301393, 2022).
Hypertension (18 papers, 2012 to 2024). The presence of chronic increased pressure in the systemic arterial system. "The present study has provided evidence suggesting that impaired trophoblast invasion in hypertensive disorders in pregnancy is associated with reduced MMP-1 levels in trophoblasts and decidual cells." (PMID 25667666, 2015). "Elevated serum levels of MMP-1 occurring in hypertension may be associated with increased collagen degradation in cardiovascular disease in the extracellular matrix." (PMID 36362588, 2022). "Regarding the observed possible association of MMP-1 with hypertension among our results, it is worth noting that according to the literature, its expression is increased in human vascular smooth muscle cells exposed to angiotensin II, as has been described in cases of hypertension." (PMID 35769087, 2022). "This hypertension-associated increase in TIMP-1 may contribute to an altered MMP-1/TIMP-1 ratio that already favors ECM increase over degradation." (PMID 32039229, 2019). "The results of the present study demonstrated that the expression levels of MMP-1 in the umbilical cord blood, placenta and decidua of patients with hypertension disorder in pregnancy were clearly lower than those in patients with normal pregnancy (P<0.05)." (PMID 25667666, 2015). "The levels of MMP-1 in the hypertensive disorders in the pregnancy and control groups exhibited positive correlations with the MMP-1 levels in the placenta (r=0.921, P<0.05), and also in the decidua (r=0.885, P<0.05)." (PMID 25667666, 2015). "The positive expression rate of MMP-1 in the placenta and decidua of patients with hypertensive disorders in pregnancy was lower than that of the controls (P<0.01 and P<0.01, respectively)." (PMID 25667666, 2015). "The levels of TIMP-1 in the hypertensive disorders in pregnancy and control groups exhibited positive correlations with the MMP-1 levels in the placenta (r=0.891, P<0.05) and the decidua (r=0.914, P<0.05)." (PMID 25667666, 2015). "In hypertensive HF patients, the serum CITP:MMP-1 ratio was inversely associated with the risk for HF hospitalization and the combination of an increased cross-linking and a high collagen type I deposition was associated with a higher risk for HF hospitalization and mortality." (PMID 37685762, 2023). "Higher concentrations of TIMP-1, an inhibitor of MMP-1 seen in hypertension and keloid fibroblasts, may reduce turnover of type 1 collagen, which is present at higher levels in KLs." (PMID 32039229, 2019). "This suggests an interplay between these factors that may be mediated by an altered MMP-1/TIMP-1 ratio that favors ECM deposition, and hypertension-associated tissue hypoxia that increases HIF-1 expression that influences the development of aberrant keloid fibroblasts and myofibroblasts." (PMID 32039229, 2019). "However, there are few studies regarding MMP-1 and hypertensive disorders in pregnancy." (PMID 25667666, 2015). "Serum ratio CITP:MMP1 was presented as a strong biomarker relating myocardial fibrosis in patients with heart failure and hypertension, however, in our current study, the serum ratio CITP:MMP1 was similar between different stages of AF and the control group." (PMID 35159236, 2022). "It is speculated that MMP-1 and TIMP-1 may be involved in the occurrence and development of hypertension disorders in pregnancy in every part of the maternal-fetal interface." (PMID 25667666, 2015). "In the last years, MMP-1 and TIMP-1 (the inhibitor of soluble MMPs but not of MT-MMP), have been one of the most studied for hypertension-mediated damage to vessels and target organs." (PMID 35324807, 2022).
squamous cell carcinoma (18 papers, 1998 to 2025). A carcinoma arising from squamous epithelial cells. "MMP1, produced by tumor cells, facilitates the hematogenous spread of squamous cell carcinoma (SCC) by inducing vascular permeability through endothelial protease-activated receptor (PAR)-1, aiding invasion and metastasis." (PMID 40809844, 2025). "An upregulated expression of MMP-1, MMP-2, and MMP-13 is associated with different malignant pathologies, such as squamous-cell carcinomas of the mouth." (PMID 39596178, 2024). "The expression of MMP1 is upregulated in oral lichen planus, dysplasia, squamous cell carcinoma, and lymph node metastasis." (PMID 34445346, 2021). "Among these, MMP12, AURKB, SERPINE1, and MMP1 have been confirmed to play important roles in squamous cell carcinoma including LSCC." (PMID 33680908, 2020). "Others have provided additional confirmation for Snail in inducing MMP-1, -2, -7 and -14 in liver and squamous cell carcinoma lines as well as MMP-9 in MDCK epithelial cells." (PMID 26932374, 2014). "In 1998, the results of a study comparing OLP, dysplasia and squamous cell carcinoma (SCC) revealed that MMP-1, MMP-2, and MMP-3 expression were lower in OLP than SCC, and MMPs and TIMPs were clearly upregulated during invasion in oral SCC." (PMID 22737547, 2012). "During collective cellular migration, which is the predominant pattern adopted by squamous cell carcinoma, MMP1 interacts with integrin α2β1 at the leading edge, and degrades native matrix macromolecules into fragments that are subsequently processed by the gelatinases MMP2 and MMP9." (PMID 24063540, 2013). "MMP1 gene expression has been shown to be up-regulated also in ADC and squamous cells carcinoma tissues as compared to normal lung." (PMID 33905434, 2021). "An expression of MMP-1 (interstitial collagenase), MMP-2 (72-kDa type IV collagenase) and MMP-3 (stromelysin-1) was investigated in squamous cell carcinoma (SCC) and its precancerous condition, actinic keratosis (AK), using in situ hybridization techniques." (PMID 10362121, 1999). "The finding of keratin genes, ACTB, and MMP1 as SPGs is not surprising, as they have been known to be involved in cellular organization functions, particularly in squamous cell carcinoma." (PMID 37371475, 2023). "In addition, inhibition of p38 and ERK in a squamous cell carcinoma cell line SCL-1 has been shown to inhibit UV-A and UV-B-induced matrix metalloproteinases MMP-1 (stromelysin-2) and MMP-10 (interstitial collagenase) expression both in vitro and in vivo." (PMID 22312244, 2012).
idiopathic pulmonary fibrosis (17 papers, 2008 to 2025). Idiopathic pulmonary fibrosis (IPF) is a nonneoplastic pulmonary disease that is characterized by the formation of scar tissue within the lungs in the absence of any known cause. "Intriguingly, previous research found that MMP-1 was highly upregulated in idiopathic pulmonary fibrosis (IPF), which shares similar pathological features to radiation-induced pulmonary fibrosis, the later stage of RILI." (PMID 27659527, 2016). "Studies on certain molecules, particularly matrix metalloproteinases (such as MMP-7 and MMP-1) and Krebs von den Lungen-6 (KL-6), suggest that these molecules could be used as biomarkers in idiopathic pulmonary fibrosis (IPF) in the near future." (PMID 39597967, 2024). "In lungs with usual interstitial pneumonia (UIP), MMP1, MMP2 and MMP9 are highly expressed." (PMID 28098218, 2017).